LDHA (lactate dehydrogenase A)
Description:
Interconverts simultaneously and stereospecifically pyruvate and lactate with concomitant interconversion of NADH and NAD(+).
Synonyms: PIG19; GSD11; HEL-S-133P; LDHM
Tractability: Small molecule: a structure with a bound ligand is known; a high-quality ligand is known; it has a high-quality binding pocket; it belongs to a druggable protein family. PROTAC: UniProt records ubiquitination sites on it; ubiquitination databases record sites on it; its protein half-life has been measured; a small molecule that binds it is known.
Target class: Enzyme; Oxidoreductase
Gene: Protein-coding gene on chromosome 11 (18,394,347 to 18,408,425, forward strand). Ensembl gene ENSG00000134333.
Subcellular location: Cytoplasm
Subcellular location (Human Protein Atlas): Cytosol
Pathways (Reactome):
Metabolism: Pyruvate metabolism; Regulation of pyruvate metabolism
Gene Ontology:
Molecular function: cadherin binding; identical protein binding; L-lactate dehydrogenase (NAD+) activity; protein binding; catalytic activity; lactate dehydrogenase activity; oxidoreductase activity; oxidoreductase activity, acting on the CH-OH group of donors, NAD or NADP as acceptor
Biological process: lactate metabolic process; glycolytic process; pyruvate catabolic process
Cellular component: cytosol; extracellular exosome; membrane; nucleus; oxidoreductase complex; mitochondrion; cytoplasm; sperm fibrous sheath
Genetic constraint (gnomAD): Loss-of-function variants: 8 observed, 23.53 expected, observed/expected ratio (o/e) 0.34, 90% interval 0.2 to 0.61. The upper end of that interval is the gene's LOEUF score, 0.61, which puts it in group 2 of 6, group 1 being the genes least tolerant of losing a copy. Missense variants: 181 observed, 283.88 expected, observed/expected ratio (o/e) 0.64, 90% interval 0.56 to 0.72. Synonymous variants: 79 observed, 96.46 expected, observed/expected ratio (o/e) 0.82, 90% interval 0.68 to 0.99.
Homologues: Orthologues: chimpanzee LDHA (99% identical), guinea pig LDHA (95% identical), mouse Ldha (94% identical), pig LDHA (93% identical), tropical clawed frog ldha (85% identical), zebrafish ldha (76% identical). Paralogues in human: LDHB (76% identical), LDHC (75% identical), LDHAL6A (73% identical), LDHAL6B (71% identical), MDH2 (26% identical).
Diseases named in the same sentence as LDHA in open-access papers:
LDHA is named in the same sentence as 308 diseases in open-access papers, as found by Europe PMC text mining. Sharing a sentence is not in itself a finding about the gene and the disease. The quoted sentences say what the papers report.
breast cancer (274 papers, 2010 to 2026). A primary or metastatic malignant neoplasm involving the breast. "One of them is circ-CSNK1G1, which, through the suppression of miR-28-5p, causes overexpression of the LDHA gene in breast cancer, leading to increased proliferation, migration, and invasion." (PMID 40563399, 2025). "HK2, PKM2, and LDHA, glycolysis-associated proteins, affect tumorigenesis, cell growth, migration, autophagy of breast cancer." (PMID 34951340, 2022). "ETV4 loss significantly inhibits the expression of HK2, LDHA as well as other glycolytic enzymes, reduces glucose uptake and lactate release in breast cancer cells." (PMID 34052833, 2021). "Aberrantly high expression of LDHA has been demonstrated in multiple cancers, including breast cancer, and it has been associated with malignant tumor progression." (PMID 33714987, 2021). "Invasive front of the tumor showed cell-specific protein localization of LDHA in breast cancer cells and LDHB in cancer-associated adipocytes." (PMID 33353120, 2020). "High serum epinephrine is associated with poor prognosis and activated LDHA/USP28/MYC/SLUG signaling axis in breast cancer patients." (PMID 30688660, 2019). "It has been reported that upregulation of lactate dehydrogenase-A, which plays a key role in the glycolytic pathway for regulating the conversion of pyruvate to lactate, causes resistance to paclitaxel in breast cancer treatment." (PMID 28283035, 2017). "In summary, our study detected a high expression level of LDHA in breast cancer, which was associated with poor clinical outcomes." (PMID 26902416, 2016). "LDHA was associated with Beclin-1 to provoke pro-survival autophagy in TAM resistant breast cancer." (PMID 40612109, 2025). "Furthermore, in tissue samples from breast cancer patients, phosphorylated LDHA is strongly linked with the development of metastases." (PMID 40295451, 2025). "Furthermore, AI-resistant breast cancer cells maintain a relatively high NAD+/NADH ratio due to enhanced lactate synthesis caused by increased LDHA expression." (PMID 40303296, 2025). "The results showed that LDHA expression was markedly increased in patients at tumor advanced-stage or in metastatic tumors, and high expression of LDHA was significantly associated with short overall survival of breast cancer patients (P < 0.0001)." (PMID 34178639, 2021). "In breast cancer cells, acute and chronic hypoxia promote alternative LDHA-001 (alternative first exon) splicing and reduce LDHA-201 (intron 1-retained) isoform expression, leading to loss of LDHA-201 expression through NMD." (PMID 32536347, 2020). "Importantly, the same authors determined that the level of LDHA phosphorylation at Y10 was directly associated with the progression of metastatic disease in a cohort of breast cancer patient biopsies." (PMID 31139559, 2019). "Thus, the LDHA-lowering agent vitamin C can be a potential approach for combating stress-associated breast cancer." (PMID 30688660, 2019). "LDHA is associated with breast cancer resistance to paclitaxel/trastuzumab and myeloma relapse; overexpression of hexokinase 2 (HK2) is involved in cisplatin resistance in ovarian cancer cells, by enhancing autophagy and the increased expression of PDK2 is linked to paclitaxel resistance in NSCLC." (PMID 30873026, 2019). "Importantly, we suggest that vitamin C, which targets this pathway by inhibiting LDHA, is a potential treatment for the stress-associated increase in breast cancer." (PMID 30688660, 2019). "Importantly, in head and neck cancer, as well as in breast cancer cell lines, the expression of Y10-phosphorylated LDHA was positively associated with cell invasion ability and anoikis resistance." (PMID 31139559, 2019). "Here, we investigate the roles of LDHA and the association of miR-34a and LDHA in breast cancer." (PMID 26902416, 2016).
breast cancer (continued). "Moreover, c-Src also phosphorylates LDHA at Y10, increasing its activity, which correlates with metastasis progression of clinical tumor samples of breast cancer, while as shown here, the dominant-negative variant of c-Src, the SrcDN counteracted these effects." (PMID 32673341, 2020). "LDHA is overexpressed in many cancer cells, including kidney cancer, breast cancer, and colorectal cancer, and promotes cancer development and progression." (PMID 41507134, 2026). "Mechanistically, YTHDF3 enhances the expression of HIF1α and LDHA and glycolysis by inducing the phosphorylation of mTOR, and finally promotes the occurrence and development of breast cancer." (PMID 42036761, 2026). "Phosphorylation, notably at Y10, potently activates LDHA, driving processes like invasion and anoikis resistance in breast cancer." (PMID 41454479, 2026). "In this study, we elucidated that YTHDF3 regulates the glycolysis level, proliferation and migration of breast cancer through the mTOR-HIF1α-LDHA axis." (PMID 42036761, 2026). "In breast cancer, POU1F1 transcription factor in breast cancer cells enhances LDHA expression and promotes pro-lactate and secretion into the TAM." (PMID 40565047, 2025). "Specifically, chronic stress was found to stimulate lactate production in breast cancer by elevating lactate dehydrogenase A (LDHA)." (PMID 40387308, 2025). "Beclin-1, a key protein involved in autophagosome formation, interacts with LDHA and activates it to promote autophagy in breast cancer cells, thereby increasing their resistance to TAM51." (PMID 40303296, 2025). "Research has shown that the phosphorylation of LDHA at tyrosine- 10 (Y10) increases its catalytic activity, increasing the capacity of breast cancer cells for metastasis and resistance to anoikis." (PMID 40295451, 2025). "Through the increase in HSF1, ErbB2 overexpression increases LDHA, which in turn leads to an increase in glycolysis in human breast cancer cells." (PMID 40295451, 2025). "The data obtained show that, through its tumor-suppressive effect on LDHA, miR-28-5p inhibits breast cancer development." (PMID 40563399, 2025). "The protein levels of LAT1, p-PKM2, and p-LDHA were determined in breast cancer tissue arrays by immunohistochemistry staining followed by survival analysis." (PMID 40611146, 2025). "The glycolytic enzyme lactate dehydrogenase A (LDHA) is also closely associated with numerous tumours including pancreatic cancer, GC, HCC, breast cancer and lung cancer." (PMID 40845073, 2025). "This activation increases the expression of numerous genes in the downstream and enhances LDHA, fostering breast cancer's growth, penetration and spread." (PMID 41190507, 2025). "Lactylation promotes proliferation and invasion in breast cancer cells, particularly under hypoxic conditions, with H3K9la and LDHA upregulation enhancing tumor invasiveness and immune evasion." (PMID 41458606, 2025). "NAT10 upregulated JunB expression by increasing ac4C modification levels on its mRNA, further up-regulated LDHA expression and facilitated glycolysis in breast cancer." (PMID 40588654, 2025). "In breast cancer, aberrant expression of LDHA-mediated glycolysis is correlated with the acquisition of TAM resistance in breast cancer." (PMID 40264038, 2025). "This, in turn, upregulates LDHA expression and initiates glycolytic metabolism in AI-resistant breast cancer cells." (PMID 40303296, 2025). "Another example of the effect of miR-28-5p on breast cancer progression is its regulation of the LDHA gene, which is overexpressed in various types of cancer and is associated with a poorer patient prognosis." (PMID 40563399, 2025). "Research has revealed that LDHA inhibits the invasion of antitumor immune cells and promotes the maintenance of breast cancer stemness." (PMID 40295451, 2025).
breast cancer (continued). "Another strong LDHA inhibitor that has been thoroughly investigated in TNBC and ER +/PR + breast cancer is N-hydroxy indole (NHI), and FX- 11, a gossypol analog that targets LDHA, has been thoroughly investigated in ER +/PR + breast cancer." (PMID 40295451, 2025). "According to another investigation, KCNK1 activates LDHA and upregulates H3 K18 lactylation to stimulate the growth and metastasis of breast cancer cells." (PMID 40295451, 2025). "KCNK1, a K2P channel member, is highly expressed in breast cancer and promotes metabolic reprogramming through activation of lactate dehydrogenase A (LDHA)." (PMID 41155636, 2025). "Intriguingly, stress-induced epinephrine enhances breast cancer stem-like characteristics through LDHA (lactate dehydrogenase A) - dependent metabolic reprogramming." (PMID 40129916, 2025). "LDHA plays a pivotal role in the induction of tumorigenesis, and studies have shown that its overexpression in breast cancer correlates with increased cell proliferation and accelerated tumor growth." (PMID 40563399, 2025). "IHC staining of the breast cancer tissue arrays showed that p-LDHA (Tyr10) expression was elevated in Luminal, HER2 +, and TNBC tissues compared to normal breast tissues, with TNBC showing the highest levels of expression." (PMID 40611146, 2025). "Survival analysis of TCGA data indicated that, in the basal subtype of breast cancer, patients with high LDHA expression had significantly shorter OS compared to those with lower LDHA expression." (PMID 40611146, 2025). "The inactivation of LDHA has been discovered to impede tumorigenesis and progression within tumor mouse models, underscoring the crucial role played by LDHA in promoting K-RAS induced primary breast cancer in mice." (PMID 39897050, 2025). "Galloflavin has been shown to connect with free LDHA and block glycolysis in breast cancer cells, thereby reducing cancer development." (PMID 40956032, 2025). "LDHA has been noted to be overexpressed in several cancers, such as breast carcinoma, cervical carcinoma, pancreatic carcinoma, and glioma." (PMID 40956032, 2025). "DTL reprograms glycolysis by interacting with LDHA directly in breast cancer (BC) cells, leading to increased production of the oncometabolite L-lactate, which drives tumor progression." (PMID 40391156, 2025). "Of note, the expression of lactate dehydrogenase A (LDHA) in breast cancer tissues is much higher than that in adjacent tissues, and it can maintain cancer stemness and promote the plasticity of breast cancer stem cells." (PMID 38680483, 2024). "This study shows that KCNK1 is overexpressed in breast cancer promoting proliferation, invasion and metastasis by increasing glycolysis and activating Lactate Dehydrogenase A." (PMID 38905316, 2024). "All these data strongly support that LDHA mediated the functions of KCNK1 on the progression of breast cancer." (PMID 38905316, 2024). "Knockdown of circABCB10 led to decreased protein levels of glycolysis-related factors, such as HIF1a, HK2, and LDHA, resulting in enhanced radiosensitivity of breast cancer cells." (PMID 38408962, 2024). "Further studies unexpectedly revealed that KCNK1 contributed to the malignant phenotype of breast cancer by binding to and activating LDHA." (PMID 38905316, 2024). "Subsequently, we evaluated the metabolic and proliferative functions upon FASN and LDHA inhibition in breast cancer models." (PMID 39044184, 2024). "Transwell invasion assays also demonstrated that overexpression of LDHA rollbacked the attenuated invasion ability of breast cancer cells induced by the knockdown of KCNK1." (PMID 38905316, 2024). "Up-regulation of LDHA expression activates the glycolytic pathway and also enhances the resistance of breast cancer cells to aromatase agents." (PMID 38709280, 2024).
breast cancer (continued). "In breast cancer, lactate dehydrogenase A (LDHA) induction increases lactate production and chemokine ligand 2 (CCL2) secretion, thereby promoting TAM infiltration, particularly the M2 phenotype." (PMID 39227970, 2024). "In the case of breast cancer, miR-34a was also found to suppress LDHA expression, suggesting a potential mechanism for enhancing the sensitivity of breast cancer cells to radiation therapy by inhibiting glucose metabolism." (PMID 38408962, 2024). "Among the genes of the five proteins selected, GPI, LDHA, TPI1, and ALDOA showed high expression in both breast cancer and colorectal cancer and were associated with poor patient prognosis." (PMID 38419074, 2024). "Regular stress-induced adrenaline can activate LDHA upregulation, promoting glycolysis in mammary tumors." (PMID 38831236, 2024). "Wound healing and transwell migration assays also showed that LDHA reversed the inhibitory effect of KCNK1 knockdown on the migration ability of breast cancer cells." (PMID 38905316, 2024). "A previous study revealed that chronic stress-induced epinephrine promoted the deubiquitylation of MYC by USP28 via lactate dehydrogenase A (LDHA)-dependent metabolic reprogramming in breast cancer." (PMID 38689092, 2024). "In a breast cancer model, LDHA knockdown can weaken glycolysis and significantly reduce tumor growth by affecting mitochondrial physiology." (PMID 39582531, 2024). "The results of the GEPIA analysis revealed a correlation between TIGIT expression and the down-regulation of HK2 and LDHA in breast cancer tissues." (PMID 38216949, 2024). "The data showed that overexpression of LDHA reduced the adhesion and stiffness of breast cancer cells that were enhanced by KCNK1 knockdown." (PMID 38905316, 2024). "miRNAs can be used as tumor suppressors to inhibit the expression of LDHA, weaken the Warburg effect in tumors, and inhibit the growth and metastasis of breast cancer." (PMID 37204526, 2023). "Clinical aggression is determined by the anaerobic tumor metabolism driven by lactate dehydrogenase (LDHA) and the hypoxia-inducible factor HIF1alpha, as found in 175 breast cancer patients treated in a prospective study." (PMID 36976529, 2023). "The progression of breast cancer (BC) metastasis is positively correlated with the phosphorylation of enzyme LDHA at Y10." (PMID 37384249, 2023). "Among different LDH isoforms, lactate dehydrogenase A (LDHA) is overexpressed in breast cancer cells and facilitates the glycolytic process by converting pyruvate to lactate." (PMID 37444501, 2023). "Chronic stress-induced epinephrine promoted breast cancer stem-like properties via LDHA-dependent lactate dehydrogenase metabolic rewiring." (PMID 37275984, 2023). "LDHA expression was up-regulated in breast cancer and correlated with poor clinical outcomes of breast cancer." (PMID 35278714, 2023). "MORC2 then interacts with the transcription factor c-Myc and is recruited to the LDHA promoter to control the expression of LDHA, which is responsible for the migration of breast cancer cells." (PMID 37892209, 2023). "A dietary polyphenolic compound, quercetin, suppressed growth and migration by inhibiting PFKP and LDHA expression in breast cancer." (PMID 37151384, 2023). "Simultaneous overexpression of PFKP and LDHA has previously been described in a breast cancer cell line (MDA‐MB‐231), in which PFKP regulation also affects lactate production." (PMID 37326348, 2023). "Knockdown of LDHA in ErbB2-transformed mouse mammary tumor cells inhibited their tumorigenicity, suggesting that ErbB2 induces mammary tumorigenesis through, at least in part, LDHA." (PMID 37444501, 2023).